USP15 (ubiquitin specific peptidase 15)
Diseases named in the same sentence as USP15 in open-access papers (continued):
Sharing a sentence is not in itself a finding about the gene and the disease.
lung carcinoma (8 papers, 2018 to 2025). "This study demonstrates that USP15 is negatively implicated in lung cancer progression through the regulation of TRAF6-BECN1 signaling for autophagy induction for the first time." (PMID 35422093, 2022). "With USP15KO A549 and USP15KO H1299 lung cancer cells, we preliminary assessed whether USP15 deficiency affected lung cancer invasion using a transwell invasion assay." (PMID 35422093, 2022). "Based on these findings and previous reports, we investigated whether USP15 as a deubiquitinating enzyme was implicated in lung cancer progression, especially through the regulation of TRAF6-BECN1 signaling axis for autophagy induction." (PMID 35422093, 2022). "Consistently, USP15 was significantly downregulated in patients with primary lung adenocarcinoma, strongly suggesting that USP15 might be functionally associated with lung cancer." (PMID 35422093, 2022). "Interestingly, USP15 amplification is reported in certain cancers, and here we show this is also the case for lung cancer, where elevated USP15 is associated with worse prognosis in clinical lung adenocarcinoma." (PMID 29429988, 2018). "Similarly, the invasion ability of USP15KO H1299 cells was also significantly higher than that of Ctrl H1299 cells (USP15KO H1299 vs. Ctrl H1299 cells), suggesting that USP15 might be functionally implicated in lung cancer invasion." (PMID 35422093, 2022). "Based on the molecular mechanism by which USP15 is negatively implicated in the autophagy induction through deubiquitination of BECN1, our study suggests that the negative regulation of USP15 in lung cancer progression might be functionally implicated in the regulation of autophagy induction." (PMID 35422093, 2022). "For example, USP4 and USP15 promoted the growth of lung cancer cells via measuring selective splicing of SRSF1." (PMID 38581057, 2024). "After knocking out deubiquitinating enzyme USP15 by CRISPR technology, TLR4 stimulation induces autophagy of NSCLC cell lines, thus increasing their migration and invasion, and USP15 is identified as a tumor suppressor in lung cancer progression." (PMID 38188023, 2023). "For the clinical significance of USP15 in lung cancer, we checked the USP15 correlation with LUAD development and the patient’s survival by analyzing the TCGA LUAD data, especially PanCancer Atlas using cBioportal." (PMID 35027535, 2022). "Eventually, USP15 can negatively regulate lung cancer progression by inhibiting the TRAF6-BECN1 signaling axis through autophagy induction." (PMID 35422093, 2022). "We found that SRSF1 is upregulated in several lung cancer cells compared to the normal lung epithelial cells, similar to the USP15 and USP4 expression patterns." (PMID 35027535, 2022). "First, we examined the endogenous expression level in different lung cancer cells and found that both USP15 and USP4 overexpresses in the NSCLC cell lines; A549, H157, and H1299 compared to the normal lung epithelial L132 cell." (PMID 35027535, 2022). "We observed an increased endogenous expression of SRSF1 in lung cancer cells as well, and its overexpression significantly enhanced cancer cell phenotype and rescued the depletion effect of USP15 and USP4." (PMID 35027535, 2022). "Collectively, we concluded that the oncogenic property of USP15 and USP4 is associated with SRSF1 that shows a parallel regulatory effect in lung cancer cell while the alternatively spliced isoform SRSF1-3 lacks such oncogenic functions." (PMID 35027535, 2022). "The expression of USP15 was markedly lower in those with lung cancer than in normal controls (27.29 in lung cancer vs. 64.76 in normal controls)." (PMID 35422093, 2022). "Clinical data of the TCGA and primary non-small cell lung cancer (NSCLC) patients (n = 41) revealed that the expression of USP15 was significantly downregulated in lung cancer patients." (PMID 35422093, 2022).
lung carcinoma (continued). "All three shRNAs identified in the secondary DUB screen (DUB2 sub-library) downregulated USP15 mRNA expression in freshly isolated, lentiviral-infected Lin− cells and USP15 protein levels in primary murine lung cancer cells." (PMID 33378683, 2020). "To explore the relative cellular abundance of the two USP15 isoforms in lung cancer, we used quantitative real-time RT-PCR (qRT-PCR) with primers that specifically detect the splice variants encoding USP15 isoform-1 or isoform-2." (PMID 29429988, 2018). "Regarding clinical aspects, primary LUAD patients (n = 4) with low expression of USP15 showed significant upregulation of genes (n = 10) involved in the promotion of lung cancer proliferation, migration, invasion, and metastasis, whereas tumor suppressor genes (n = 10) were downregulated." (PMID 35422093, 2022). "Having shown that USP15 negatively regulated lung cancer migration and invasion induced by TLR4 stimulation through inhibition of autophagy induction, we next explored the molecular mechanism in which USP15 was implicated in autophagy induction by TLR4 stimulation." (PMID 35422093, 2022). "Having found that USP15KO A549 and USP15KO H1299 lung cancer cells exhibited increased cancer invasion, we further examined whether USP15 affected lung cancer migration and invasion through autophagy induction by TLR4 stimulation." (PMID 35422093, 2022). "Finally, we asked whether USP15 may be dysregulated in lung cancer in a way that might promote genome instability." (PMID 29429988, 2018). "High expression of USP15, along with its close paralog USP4, has been reported to promote lung cancer cell proliferation." (PMID 40762380, 2025). "In summary, we found that the deubiquitinating enzymes USP15 and its close paralog USP4 regulate alternative splicing of SRSF1 resulting in the isoform-specific functions in lung cancer cell." (PMID 35027535, 2022). "In addition, the survival rate from combined patients with LUAD and LUSC decreased in patients with low expression levels of USP15 (blue line with low USP15 vs. red line with high USP15), indicating that USP15 expression may have an essential role in lung cancer patient’s survival." (PMID 35422093, 2022). "Here, we found that USP15 and its close paralog USP4 are overexpressed and facilitate lung cancer cell proliferation by regulating the alternative splicing of SRSF1." (PMID 35027535, 2022). "Given the results that USP15 negatively regulated lung cancer migration and invasion through inhibition of autophagy induction by deubiquitination of BECN1, we tried to find the clinical relevance of USP15 in the regulation of lung cancer progression." (PMID 35422093, 2022). "Regarding the cellular function of USP15 in lung cancer progression, notably, USP15KO A549 and USP15KO H1299 lung cancer cells exhibited increases in cancer invasion that were markedly enhanced in response to TLR4 stimulation after treatment with LPS." (PMID 35422093, 2022). "Collectively, our current study demonstrates USP15 and USP4 mediated lung cancer cell proliferation and migration by increasing the expression of functional full-length SRSF1 protein." (PMID 35027535, 2022). "In summary, we proposed a possible mechanism by which USP15 regulates TRAF6-BECN1 signaling in autophagy induction and lung cancer progression." (PMID 35422093, 2022). "Collectively these data suggest that both USP15 and USP4 genes are overexpressed and facilitate lung cancer cell progression." (PMID 35027535, 2022). "In this study, we found that USP15 and USP4 regulate alternative splicing of SRSF1 resulting in the isoform-specific functions in lung cancer cell proliferation and migration." (PMID 35027535, 2022). "Notably, the profound impact of USP15 expression was shown in USP15KO A549 and USP15KO H1299 lung cancer cells." (PMID 35422093, 2022).
lung carcinoma (continued). "We observed an increased expression of BIN1 through SRSF1 downregulation by USP15 and USP4 knockdown, which may, in turn, inhibits the metastatic ability of lung cancer cells." (PMID 35027535, 2022). "Importantly, USP15-knockout (USP15KO) A549 and USP15KO H1299 lung cancer cells generated with CRISPR-Cas9 gene-editing technology showed increases in cancer migration and invasion with enhanced autophagy induction in response to TLR4 stimulation." (PMID 35422093, 2022). "Herein, we provide novel molecular and cellular mechanisms involved in the negative effect of ubiquitin-specific peptidase 15 (USP15) on lung cancer progression." (PMID 35422093, 2022). "Importantly, USP15-knockout (USP15KO) A549 and USP15KO H1299 lung cancer cells generated by CRISPR-Cas9 gene editing showed increases of cancer migration and invasion accompanied by enhanced autophagy induction in response to TLR4 stimulation." (PMID 35422093, 2022).
melanoma (8 papers, 2017 to 2024). A malignant, usually aggressive tumor composed of atypical, neoplastic melanocytes. "The more interesting ones, confirmed by the bibliography on melanoma, are as follows: USP15, TIPIN, TMC5, TYMP, USP19, USP8, and TFAP2B." (PMID 38928466, 2024). "Multiple oncogenic pathways have been found to regulate TBX3 expression in occurrence of melanoma, lung, thyroid, breast and other types of cancers, here we define USP15 as a critical stabilizer for TBX3." (PMID 38750011, 2024). "Take melanoma as another model where BRAFV600E-induced BRAF/MAPK activation is also the most dramatic carcinogenic mutation, we found knock-down of USP15 resulted in significant TBX3 reduction." (PMID 38750011, 2024). "Clinically, TBX3 level positively correlates with that of USP15 as well on our melanoma tissue array." (PMID 38750011, 2024). "Similar to the regulatory mechanism under BRAFV600E–induced thyroidal transformation, USP15 is also transcriptionally activated by BRAF/MAPK pathway during melanoma genesis and controls TBX3 stability." (PMID 38750011, 2024). "In Usp15 −/− (KO) mice as compared to wild-type (WT) mice and after B16 injection, the growth curve of melanoma cells was profoundly reduced with a prolonged lifespan." (PMID 35884430, 2022). "Evidence regarding the relationship between USP15 and the melanoma immune response is based on two investigations." (PMID 35884430, 2022). "The knockdown of USP15 results in the decrease in the E3 ubiquitin ligase MDM2 protein in the melanoma cell line A375 and the colorectal cancer cell line HCT116, indicating that USP15 plays an important role in stabilizing MDM2." (PMID 35203682, 2022). "The USP15 gene is unusually composed of 22 exons for which eight human isoforms have been described, which may imply specific functions for those isoforms in melanoma." (PMID 35884430, 2022). "Then, the role of USP15 in regulating antitumor host defences was proved in a B16 melanoma model." (PMID 28544818, 2017). "At this stage, USP15 in melanoma appears to be involved in the anti-tumor immune response and its targeting could be a useful strategy to inhibit growth by inducing apoptosis of tumor cells by activating anti-tumor immunity and/or by boosting the efficacy of existing immunotherapy." (PMID 35884430, 2022). "Therefore, targeting USP15 could be a valuable strategy for restraining melanoma growth by activating antitumor immunity." (PMID 28544818, 2017). "Indeed, the abundant expression of USP15 and TBX3 concurs apparently through BRAFV600E positive cancer cells, such as melanoma cells A2058, OCM-1, A375, besides thyroid cancer cells K1, BCPAP, 8505 C." (PMID 38750011, 2024). "USP15 stabilizes MDM2 and induces the apoptosis of melanoma and colon cancer cells." (PMID 36163170, 2022). "Murine or human melanoma cells lacking USP15 were found to exhibit a proliferation arrest and an apoptotic induction in vitro with reduced tumor growth in nude mouse xenografts in vivo." (PMID 35884430, 2022).
Parkinson disease (7 papers, 2017 to 2025). A progressive degenerative disorder of the central nervous system characterized by loss of dopamine producing neurons in the substantia nigra and the presence of Lewy bodies in the substantia nigra and locus coeruleus. "USP15 promotes tumor cell survival in several human malignancies, and its functional deficiency significantly reversed mitophagy defects in Parkinson’s disease (PD) patients." (PMID 36635430, 2023). "Thus, the gene USP15 is associated with fertility traits in bulls and plays a role in regulating Parkinson’s disease, viral infections, and cancer-related signaling networks in humans." (PMID 40805107, 2025). "Knockdown of USP15 can rescue the mitophagy defect in fibroblasts of patients with Parkinson’s disease (PD) and increase their parkin levels." (PMID 35422093, 2022). "USP15 is also dysregulated in many cancers (12, –, 14), and knockdown of USP15 rescues the mitophagy defect of Parkinson's disease patients' fibroblasts." (PMID 30228188, 2018). "USP15 can deubiquitinate PARKIN to impair mitochondrial autophagy, suggesting that USP15 inhibition could be a therapeutic strategy for Parkinson’s disease, caused by reduced PARKIN levels." (PMID 35203682, 2022). "Besides its oncogenic role, USP15 also antagonizes the E3 ubiquitin ligase Parkin-mediated mitochondrial ubiquitination and inhibits selective autophagy of damaged mitochondria (mitophagy) in Parkinson’s disease (PD)." (PMID 33946990, 2021).
viral infection (7 papers, 2015 to 2025). "It has been documented that viral infection triggers increased interferon signalling when USP15 is lost." (PMID 38347610, 2024). "The result showed that USP15 can interact with GLTSCR2 upon viral infection." (PMID 27824081, 2016). "Consequently, miR-26a, by downregulating USP15, promotes K63 ubiquitination of RIG-I to enhance type I IFN responses, resulting in an active antiviral state against virus infection." (PMID 38019020, 2024). "Additionally, the expression of RNF12541 is induced and the expression of USP443 is reduced after viral infection, whereas, USP15 was not affected." (PMID 26061460, 2015).
pancreatic cancers (6 papers, 2018 to 2025). "As such, Usp15 appears to function as a double-edged sword in pancreatic cancer, where the loss of Usp15 enhances tumor progression in the initial stages of tumorigenesis but sensitizes to certain treatment regimens in the later stages." (PMID 38902237, 2024). "Together, these data demonstrate the tumor suppressive function of USP15 and SCAF1 in pancreatic cancer by modulating several important signaling pathways and that loss of USP15 and SCAF1 sensitizes to Gemcitabine and Olaparib." (PMID 38902237, 2024). "Here, we perform somatic CRISPR/Cas9 mutagenesis screens to assess the transforming potential of 125 recurrently mutated pancreatic cancer genes, which revealed USP15 and SCAF1 as pancreatic tumor suppressors." (PMID 38902237, 2024). "For example, USP15 is deeply deleted in 26.7% pancreas cancer patients, and USP15 Ser678 is mutated in endometrial cancer patients." (PMID 30874560, 2019). "Loss of USP15 expression renders pancreatic cancer cells sensitivity to PARP inhibitor." (PMID 30874560, 2019). "In line with the previous screen, Cdkn2a was the top-scoring gene followed by Rnf43 and the newly identified genes, Usp15 and Scaf1, further supporting their function as strong suppressors of pancreatic cancer in KC mice." (PMID 38902237, 2024). "Lastly, we set out to elucidate how Usp15 and Scaf1 regulate the response of pancreatic cancer cells to PARP inhibition." (PMID 38902237, 2024). "Lastly, we genetically ablated USP15 in patient-derived organoids (PDOs) from 3 different pancreatic cancer patients using Cas9 ribonucleotide particles." (PMID 38902237, 2024). "Further functional studies will be required to explore the relevance of SCAF1 and aberrant polyadenylation in USP15 processing and pancreatic cancer." (PMID 38902237, 2024). "Previous studies also showed that USP15 copy number is deeply depleted in almost 26.7% pancreatic cancer patients." (PMID 30874560, 2019). "Our results implied that USP15 can also be used as a biomarker for PARP inhibitor treatment in pancreatic cancers." (PMID 30874560, 2019). "We also confirmed that USP15 is down-regulated in many pancreatic cancer cell lines, especially in MIAPACA2 and PK9 cell lines." (PMID 30874560, 2019). "We also found that USP15 expression is lost or significantly decreased in a high percentage of the pancreatic cancer cell lines." (PMID 30874560, 2019). "In addition to USP15’s role in regulating sensitivity to PARP inhibition, we found that USP15 functions as a strong tumor suppressor in pancreatic cancer." (PMID 38902237, 2024). "Next, we assessed the expression of USP15 in 4 human pancreatic cancer cell lines." (PMID 38902237, 2024). "While, PANC1 and HPAFII exhibited expression of the small as well as the long USP15 isoform, MiaPACA2 and BXPC3 cells only exhibited low-level expression of the long USP15 isoform, indicating that USP15 is also downregulated in some human pancreatic cancer cell lines." (PMID 38902237, 2024). "Furthermore, overexpression of USP15 in a pancreatic cancer cell line (MIAPACA2) having low endogenous levels of USP15 rendered the cells resistance to PARP inhibitor." (PMID 30874560, 2019). "Furthermore, previous studies reported that USP15 is deeply deleted in 26.7% pancreatic cancer patients." (PMID 30874560, 2019). "Notably, USP15 and SCAF1 alterations are observed in 31% of pancreatic cancer patients." (PMID 38902237, 2024).
acute myeloid leukemia (5 papers, 2020 to 2024). Acute myeloid leukemia (AML) is a group of neoplasms arising from precursor cells committed to the myeloid cell-line differentiation. "Interestingly, several studies have reported that USP15 can modulate cellular redox reactions in acute myeloid leukemia, Huntington’s disease and diabetic nephropathy." (PMID 39522000, 2024). "We report that USP15 mRNA and protein are overexpressed in human acute myeloid leukemia (AML) as compared to normal hematopoietic progenitor cells." (PMID 34465865, 2022). "The results showed that the expression of USP15 was dramatically downregulated in acute leukemia including Acute Myeloid Leukemia (AML) and Acute Lymphoblastic Leukemia (ALL)comparing to the matched normal cells." (PMID 31952546, 2020). "Also, because USP15 is highly expressed in primary blood–derived tumors, chronic myeloid leukemia (CML) and acute myeloid leukemia (AML) patients, it can serve as a target for cancer therapy." (PMID 32354135, 2020).
cervical carcinoma (5 papers, 2014 to 2022). A carcinoma arising from either the exocervical squamous epithelium or the endocervical glandular epithelium. "USP15 also deubiquitinates and stabilizes procaspase-3 to promote paclitaxel-induced apoptosis in the human cervical cancer cell line HeLa." (PMID 35203682, 2022). "USP15 exhibits an oncogenic role in cervical cancer by promoting the stabilization of HPV oncoproteins." (PMID 33946990, 2021). "In HeLa cervical cancer cells and U2OS osteosarcoma cells, transfection of siUSP15-3 caused an almost complete loss of endogenous USP15 protein expression." (PMID 24850914, 2014). "Interestingly, the transcripts of USP15 in HPV-positive cervix cancer tissues are significantly lower than in non-tumoral normal tissue (data not shown)." (PMID 31749782, 2019).